Y_RNA (Y RNA )
Gene: Miscellaneous RNA gene on chromosome 10 (68,503,152 to 68,503,259, forward strand). Ensembl gene ENSG00000207438.
Homologues: Orthologues: macaque Y_RNA (95% identical). Paralogues in human: RNY3P14 (79% identical), Y_RNA (76% identical), RNY3 (75% identical), Y_RNA (75% identical), RNY3P4 (74% identical), Y_RNA (74% identical), RNY3P11 (73% identical), Y_RNA (73% identical), RNY3P1 (72% identical), Y_RNA (72% identical), RNY3P16 (71% identical), Y_RNA (71% identical), and 84 more.